DDX3X (DEAD-box helicase 3 X-linked)
Diseases named in the same sentence as DDX3X in open-access papers (continued):
Sharing a sentence is not in itself a finding about the gene and the disease.
cancer (continued). "Notably, another FAM83A interaction partner in primary cells is DDX3X, a molecule of interest in cancer biology for its involvement in cell cycle, apoptosis, and cell migration through regulation of transcription, mRNA maturation, mRNA export, and translation." (PMID 35183258, 2022). "Below, we will briefly summarize the known roles of DDX3X in different cancer types." (PMID 35954483, 2022). "In addition, a group of tumor suppressors that escape from X-inactivation have been implicated in cancer sex bias 30, our analysis did reveal higher expression of ATRX, DDX3X, KDM5C and KDM6A in female than male patients." (PMID 36118521, 2022). "However, the molecular mechanism of the oncogenic role of DDX3X in both types of cancers is not completely understood." (PMID 35954483, 2022). "DDX3X thus seems as a potential target for the treatment of cancer." (PMID 36402769, 2022). "Thus, DDX3X seems to assume a dual role, acting either as a promoter of cancer progression or as a tumor suppressor." (PMID 35954483, 2022). "Considering the multiple functions of DDX3X in this type of cancer, it is also impossible to predict survival outcomes of patients only using the DDX3X protein as a biomarker, since it seems to associate with different molecules that alter the tumor development." (PMID 35954483, 2022). "Moreover, a large body of data published over the years has demonstrated the roles of DDX3X in cancer biology." (PMID 35954483, 2022). "However, the genetic background present in particular cell types coupled with a modified expression and localization of DDX3X gives this protein an apparent contradictory dual role in different cancer types." (PMID 35954483, 2022). "RAC1 is another DDX3X target documented across numerous studies, regulation of which may contribute to DDX3X’s roles in neurological development, cancer cell metastasis, and macrophage phagocytosis." (PMID 36393867, 2022). "The interactome analysis of DDX3X highlighted its interaction with several miRNAs that could have an important role in the development of various types of cancer." (PMID 35954483, 2022). "Inhibiting DDX3X may restore cancer immunity and enhance the antitumor activity by inducing dsRNA-derived type I IFN response in tumors, leading to novel agents targeting DDX3X for combinatory immunotherapy." (PMID 35874614, 2022). "In addition, in HCC, reduced DDX3X expression is more common in males than in females In many cancers, DDX3X is predominantly present in the cytoplasm of cancer cells, whereas paired non-tumour tissue expresses little or no DDX3X." (PMID 33627125, 2021). "Follow-up studies that expand this work may be able to further elucidate the connections between DDX3X/Ded1, stress, and cancer." (PMID 33460649, 2021). "However, in multiple cancers, DDX3X activates β-catenin through a number of pathways to promote tumour progression." (PMID 33627125, 2021). "Over the years, DDX3X has become a molecule of interest in cancer biology." (PMID 33627125, 2021). "This aspect needs, therefore, to be considered in the hypothesis of using DDX3X inhibitors for cancer therapy in humans." (PMID 34638314, 2021). "Recently, several small molecule inhibitors of DDX3X have been described as anti-cancer agents." (PMID 34771731, 2021). "It included two established tumor suppressor escapees, in other words EXIT genes, previously suspected to be associated with excess cancer in men, namely KDM6A and DDX3X, both showing 25% higher expression in women (FC = 0.8; q = 1.7 × 10−38 and q = 1.5 × 10−15, respectively)." (PMID 33527138, 2021). "However, studies on DDX3X inhibitors and the achievements made so far have presented a new potential strategy for the treatment of cancer." (PMID 33627125, 2021). "In addition, clinical prognosis data of DDX3X has revealed a discrepancy in several types of cancers, indicating that the clinical outcomes with respect to DDX3X remain to be explored and additional evidence is required." (PMID 32326089, 2020).
cancer (continued). "Emerging evidences have also demonstrated the biological effect of DDX3X in cancer." (PMID 32326089, 2020). "Interestingly, both the oncogenic and tumor suppressive functions of DDX3X are also reported in the same kind of cancer." (PMID 32326089, 2020). "Therefore, the conflicting roles of DDX3X not only lie between cancer types but also remain inconsistent within the same type of cancer." (PMID 32326089, 2020). "DDX3X gene encodes an ATP-dependent DEAD-box RNA helicase frequently altered in various human cancers, including melanomas." (PMID 32850962, 2020). "However, the exact function of DDX3X seems to be determined by the interactive molecules and is cancer type specific." (PMID 32326089, 2020). "The results showed DDX3X expression after normalization in various types of cancer." (PMID 31906196, 2019). "In this review article, we summarized and integrated current findings relevant to DDX3X in cancer research fields, cytokines and compounds modulating DDX3X’s functions, and the released transcriptomic information and cancer patient clinical data from public databases." (PMID 31906196, 2019). "However, the results from several studies have also demonstrated that DDX3X can have a role in suppressing cancer metastasis." (PMID 31906196, 2019). "Emerging studies illustrating the role of DDX3X in cancer metastasis have been reported." (PMID 31906196, 2019). "Emerging evidence indicates the critical regulatory role of DDX3X in cancer progression." (PMID 31906196, 2019). "However, several research teams have also demonstrated that DDX3X is a biomarker of a good prognosis in cancers." (PMID 31906196, 2019). "The correlation of DDX3X with clinical prognosis has been evaluated in various types of cancer." (PMID 31906196, 2019). "When the binding of WT and RG-mutant DDX3X to 5′-UTRs of mRNAs of several cancer-related genes was compared, a clear reduction in signal could be seen in the mutant condition." (PMID 30256975, 2018). "DDX3X is a multifunctional RNA helicase with documented roles in different cancer types." (PMID 29782654, 2018). "All these database prediction data suggested that there were complicated targets interaction networks in the downstream of DDX3X-dependent miRNAs and it was worthwhile doing systematic study to analyze their regulatory relationships and exploring their potential functions in cancers." (PMID 27586307, 2016). "We also determined that cancer-associated variants did not substantially impact the ability of DDX3X to bind mRNA targets, although translation of target mRNAs was significantly impaired." (PMID 27180681, 2016). "All these findings will provide us novel insights and directions for thoroughly exploring the regulatory mechanisms of miRNA biogenesis, and shed light on effectively searching the clinical significances and biological roles of DDX3X-dependent miRNAs and their target genes in cancer development." (PMID 27586307, 2016). "So the interactions between DDX3X and its co-factors might contribute to the specificity of miRNA expression regulation in specific kinds of cancers." (PMID 27586307, 2016). "Whereas, for the expression levels of DDX3X irrelevant miRNAs, such as miR-21 and miR-155, their expression patterns were consistently up-regulated and quite opposite with DDX3X in almost all kinds of cancers." (PMID 27586307, 2016). "Above all, these data hinted that the expression changes of DDX3X-dependent miRNAs might be attributed to DDX3X level change in several human cancers, although it depends on the specificity of cancer types." (PMID 27586307, 2016). "However, for other four miRNAs, their expression levels were in accordance with DDX3X expression level only in some specific types of cancers." (PMID 27586307, 2016). "Besides, the correlations between the expression levels of DDX3X and its dependent six miRNAs in different kinds of cancers suggested that DDX3X expression level was widely down-regulated in almost 10 types of cancers." (PMID 27586307, 2016).
cancer (continued). "Ribosome profiling indicates that cancer-associated mutation impacted the translation of DDX3X targeted and non-targeted mRNAs alike, consistent with the global impairment of translation revealed by metabolic labeling studies." (PMID 27180681, 2016). "HUWE1 revealed exclusively monoallelic enrichment for all three marks, consistent with its silence on the Xi in all lines, whereas escapees SMC1A and DDX3X and several “cancer-specific” escapees displayed biallelic H3K4me3 and RNA Pol II, with monoallelic H3K27me3." (PMID 25653311, 2015). "Interestingly, we found that DDX3X induced increase of cancer cells accompanied by stem-like phenotypes such as upregulated expression of Sox2, ALDH, and CD44." (PMID 25343452, 2014). "Additionally, knockdown reduced levels of β-catenin and Rac1 proteins as well as downstream target genes, confirming the interaction of DDX3X with the Rac1/β-catenin pathway in cancer progression and indicating a potential therapeutic target for tumors with increased Wnt activity." (PMID 38539466, 2024). "Similarly, in cancer, ectopic expression of DDX3Y restores tumor growth when DDX3X is mutated." (PMID 39212449, 2024). "Avenanthramide A, the effective ingredient in avenanthramides, exhibited anti-cancer activities in CRC cells with DDX3X highly expressed via directly binding to ATP-binding domain of oncogenic protein DDX3X to block the ATPase activity of DDX3X and induce its degradation." (PMID 38023215, 2023). "Additionally, Rotterlin, a protein kinase inhibitor that exerts its anti-tumor activity in various types of human cancers, was found to upregulate DDX3X expression in HCC that subsequently downregulates cyclin D1 expression and increases p21 level, leading to cell cycle arrest." (PMID 35954483, 2022). "Furthermore, it will be interesting to examine whether cancer cells control DDX3X level or activity to evade immune detection in tumor microenvironment." (PMID 35874614, 2022). "Thus, DDX3X inhibitors are also being explored as anti-cancer drugs." (PMID 36393867, 2022). "Several independent studies suggested that DDX3X participates in cell cycle progression, apoptosis, oncogenic transformation, migration, and hypoxia response; furthermore, it is overexpressed in a large number of cancers including prostate, lung, oral, ovarian, and hepatocellular carcinoma." (PMID 34771731, 2021). "DDX3X interacts with specific components to perform both oncogenic and tumor-suppressive roles in modulating tumor proliferation, migration, invasion, drug resistance, and cancer stemness in many types of cancers, indicating the need to unravel the associated molecular mechanisms." (PMID 31906196, 2019). "On a pan-cancer scale, we replicated prior findings of sex-chromosome dosage-dependent gene essentiality in the DepMap CRISPR knockout screen in DDX3X, EIF1AX, ZFX and MAGEH117." (PMID 39975298, 2025). "FTase proteins (FNTA and FNTB) as well as eight of the 116 PFPs are known cancer-relevant proteins as per COSMIC Cancer Gene Census49 or TCGA50 (KRAS, HRAS, NRAS, RHEB, RHOA, DDX3X, ARID2, and SAV1)." (PMID 39995872, 2025). "While ADAR1, XRN1 and DDX3X are essential only in some cancer cell lines, DHX9 is more commonly essential across all cancer cell lines." (PMID 39221819, 2024). "In this study, DDX3X was characterized as a poor prognostic biomarker for an HCC patient cohort, and correlations of high DDX3X level with cancer metastasis and the activation of PCP signaling in HCC cells were discovered." (PMID 37371098, 2023). "A majorly pan-cancer positive correlation between promotor methylation and gene expression of GSDMA, CASP1, NLRP9, GZMB, DHX9, DDX3X, SFRS2IP (CASP11) and GPX4 was observed." (PMID 36605187, 2022).
cancer (continued). "The roles of two well-characterized members of this family, DDX3X and DDX5, as both oncogenes and oncosuppressors have been documented in several cancer types." (PMID 35954483, 2022). "DDX3X and DDX5 have been shown to operate in these pathways as well, with either positive or negative regulatory roles depending on the cancer type." (PMID 35954483, 2022). "Many of the genes in this category are known oncogenes or tumor suppressors (e.g., DDX3X, TRAPPC2, and TCEANC), they play crucial roles in women’s cancer." (PMID 34725332, 2021). "Despite the inability to study cancer progression per se in yeast, the high degree of sequence and functional conservation of DED1 and DDX3X argue strongly that functional defects in the mutants are likely to be conserved." (PMID 33460649, 2021). "By quantifying cancer genome evolution using the gene gravity model, we identified six putative cancer genes (AHNAK, COL11A1, DDX3X, FAT4, STAG2, and SYNE1)." (PMID 26352260, 2015). "DDX3X also acts both as an oncogene and a tumor suppressor, and high DDX3X expression can serve as a positive or negative prognostic factor, depending on the cancer type." (PMID 39975375, 2025). "DDX3X is a member of the Asp-Glu-Ala-Asp (DEAD)-box helicase family, involved in apoptosis, cell cycle, cellular stress response, and innate immunity in multiple diseases, including cancer." (PMID 38265972, 2024). "Conversely, DDX3X protein expression was lower in both normal ovarian tissues and cancer tissues, however, the difference was not statistically significant." (PMID 38603733, 2024). "This potential dependency on DDX3X for efficient translation could have profound implications for MYCN‐enhanced global protein synthesis and, consequently, the growth of these cancers." (PMID 37975412, 2024). "In the context of cancer growth, the functional interplay between MYCN and DDX3X remains enigmatic." (PMID 37975412, 2024). "Of 60 mCAs resulting in X chromosome loss (16 in 13 BL cases, 41 in 29 cancer-free controls in EMBLEM, and 3 mCAs from 3 children with non-BL cancers from Malawi), 37 (62%) affected DDX3X." (PMID 38057307, 2023). "Remarkably, the DDX3X inhibitor RK33 combined with platinum-based chemotherapy can synergistically suppress TNBC that usually expresses low levels of KLHL29 and high levels of DDX3X using cancer cell-derived xenograft and patient-derived organoids models." (PMID 37845393, 2023). "The distribution of the 30 mCA deletions affecting DDX3X was 11 of 13 BL cases, 16 of 29 cancer-free children, and 3 in all children with non-BL cancers in Malawi." (PMID 38057307, 2023). "Among the constitutive escapees, there are the highly biomedically-relevant genes DDX3X, KDM5C and KDM6A, whose escape may contribute to lower cancer incidence in females than males." (PMID 36802379, 2023). "However, by comparing the known roles of the identified interactors with those of DDX3X and DDX5 in the same cancer types, some observations can be made." (PMID 35954483, 2022). "DDX3X and DDX5 may thus be considered important nodes in the cancer pathosome, whose functions can be influenced by their interacting partners." (PMID 35954483, 2022). "In cancer, this is especially important for tumour suppressors, e.g., ATRX, DDX3X." (PMID 35661403, 2022). "Unbalanced DDX3X expression occurs in many cancer types, and DDX3 usually, but not always, provides oncogenic effects, suggesting it as a target for inhibition with small molecules." (PMID 36012592, 2022). "Both DDX3X and DDX5 interact with hundreds of different cellular proteins, and depending on the specific pathways in which they are involved, both proteins can either act as suppressors of cancer or as oncogenes." (PMID 35954483, 2022). "Targeting DDX3X impairs the CSC population in cisplatin-resistant cells via decreased expression of FOXM1 and NANOG, which are important for self-renewal properties and drug resistance in cancers that are upregulated by the m6A demethylase ALKBH5." (PMID 33627125, 2021).
cancer (continued). "DDX3X facilitates the translation of uORF-containing mRNAs by cooperating with the cap-binding protein complex (CBC) and eIF3 to enhance the metastatic ability of cancers." (PMID 33627125, 2021). "DDX3X and DDX5 are correlated with tumorigenesis in several cancers." (PMID 33608512, 2021). "The nonconventional regulatory effects include acting as a signaling adaptor molecule independent of enzymatic RNA remodeling, and DDX3X exhibits abnormal expression in cancers." (PMID 31906196, 2019). "Notably, we detected aberrant expression of XIST, the essential X-chromosome-inactivation lncRNA that is not normally expressed in males, and upregulation of genes known to escape X-inactivation, including male-biased cancer-related genes KDM6A, DDX3X, KDM5C, and ZRSR2." (PMID 42070154, 2026). "However, our findings reveal that DDX3X is not always upregulated across all cancers; in fact, it was found to be downregulated in solid tumors like PRAD and LUAD, implying its potential tumor-suppressive role." (PMID 40564907, 2025). "We hypothesize that MYCN mRNA molecules, despite their substantial production resulting from gene amplification in MYCN‐driven cancers, are not efficiently translated into proteins without the functional contribution of DDX3X." (PMID 37975412, 2024). "Understanding the interplay of the different cellular contexts, as defined by the molecular interaction networks of DDX3X and DDX5 in different tumors, with the cancer-specific roles played by these proteins could help to explain their apparently conflicting roles as cancer drivers or suppressors." (PMID 35954483, 2022). "Not surprisingly, inhibitors of DDX3X have been developed for cancer treatment." (PMID 31300642, 2019). "In addition, we present a list of interacting proteins and discuss the possible contribution of some of these protein–protein interactions in determining the roles of DDX3X and DDX5 in the process of cancer proliferation, also suggesting novel hypotheses for future studies." (PMID 35954483, 2022). "In conclusion, we believe that the analysis presented here supports the roles of DDX3X and DDX5 as important nodes in the cancer pathosome and might suggest new venues of research for a better understanding of their roles in tumor transformation and cancer progression." (PMID 35954483, 2022).